CCDC85C (coiled-coil domain containing 85C)
Description:
May play a role in cell-cell adhesion and epithelium development through its interaction with proteins of the beta-catenin family (Probable). May play an important role in cortical development, especially in the maintenance of radial glia (By similarity).
Tractability: PROTAC: ubiquitination databases record sites on it; its protein half-life has been measured.
Gene: Protein-coding gene on chromosome 14 (99,500,190 to 99,604,207, reverse strand). Ensembl gene ENSG00000205476.
Subcellular location: Cell junction, tight junction; Cell junction, adherens junction
Subcellular location (Human Protein Atlas): Cell Junctions; Nuclear speckles
Gene Ontology:
Molecular function: protein binding
Biological process: cerebral cortex development
Cellular component: adherens junction; cell junction; apical junction complex; bicellular tight junction
Genetic constraint (gnomAD): Loss-of-function variants: 18 observed, 28.19 expected, observed/expected ratio (o/e) 0.64, 90% interval 0.44 to 0.95. The synonymous counts are far from expectation, so gnomAD's model fits this gene poorly and the ratio says little. Missense variants: 566 observed, 440.13 expected, observed/expected ratio (o/e) 1.29, 90% interval 1.2 to 1.38. Synonymous variants: 264 observed, 207.15 expected, observed/expected ratio (o/e) 1.27, 90% interval 1.15 to 1.41.
Homologues: Orthologues: chimpanzee CCDC85C (100% identical), macaque CCDC85C (98% identical), pig CCDC85C (95% identical), dog CCDC85C (95% identical), mouse Ccdc85c (94% identical), rat Ccdc85c (93% identical), tropical clawed frog ccdc85c (68% identical), zebrafish ccdc85ca (63% identical), zebrafish ccdc85cb (63% identical), Caenorhabditis elegans picc-1 (25% identical). Paralogues in human: CCDC85A (45% identical), CCDC85B (25% identical).
Diseases named in the same sentence as CCDC85C in open-access papers:
CCDC85C is named in the same sentence as 7 diseases in open-access papers, as found by Europe PMC text mining. Sharing a sentence is not in itself a finding about the gene and the disease. The quoted sentences say what the papers report.
hepatocellular carcinoma (2 papers, 2021 to 2025). A malignant tumor that arises from hepatocytes. "In line with this, another study demonstrated that the transcriptional activation of VPS35 by KLF7 propels hepatocellular carcinoma cells growth and metastasis by activating Ccdc85c-medicated β-catenin pathway." (PMID 40484931, 2025). "In summary, KLF7/VPS35 axis contributes to hepatocellular carcinoma progression through CCDC85C-mediated β-catenin pathway." (PMID 33858520, 2021).
colitis (1 paper, 2024). Inflammation of the colon. "The circRNA/miRNA/mRNA competitive endogenous RNA (ceRNA) network analysis showed that the candidate miRNAs were connected to well-known colitis-associated CRC ACVR2A, SOCS1, IGF2BP1, FAM126A, and CCDC85C mRNAs, and circ-SHPRH circRNA." (PMID 38891888, 2024).
fibrosarcoma (1 paper, 2021). A malignant mesenchymal fibroblastic neoplasm affecting the soft tissue and bone. "A non-synonymous (leucine to phenylalanine, Chromosome 12-108221754) somatic SNV in Ccdc85c was detected in the BALB/cJ Meth A fibrosarcoma." (PMID 34741035, 2021).
osteoarthritis (1 paper, 2019). A noninflammatory degenerative joint disease occurring chiefly in older persons, characterized by degeneration of the articular cartilage, hypertrophy of bone at the margins and changes in the synovial membrane. "The protein CCDC85C (coiled-coil domain-containing protein 85C) was not linked to any of the 2 hallmarks and has previously been identified to be increased in patients with established RA analyzed compared with osteoarthritis (OA)." (PMID 31842970, 2019).
tumor (4 papers, 2015 to 2024). "Immunization of BALB/cJ mice with the mutated Ccdc85c 18-mer elicited potent tumor rejection or control in all mice, while the un-mutated peptide failed to elicit protection." (PMID 34741035, 2021). "Two neoepitopes, TYIRPFETKVK (derived from Ccdc85c) and HYLSSILRL (derived from Pacs2) showed the highest tumor rejection capacities." (PMID 31219806, 2019). "The second subcategory contains a reciprocal relationship between normal oesophagous and OAC where expression is reduced in the tumour samples, and hence shows an anti-correlation with FOXM1 expression, despite representing direct targets (eg AGFG2 and CCDC85C)." (PMID 25889361, 2015).
CCDC85C also shares sentences with these, for which no sentence is quoted: facial clefting (1 paper); Intellectual disability (1).